ALDH1L1 (aldehyde dehydrogenase 1 family member L1)
Description:
Cytosolic 10-formyltetrahydrofolate dehydrogenase that catalyzes the NADP(+)-dependent conversion of 10-formyltetrahydrofolate to tetrahydrofolate and carbon dioxide. May also have an NADP(+)-dependent aldehyde dehydrogenase activity towards formaldehyde, acetaldehyde, propionaldehyde, and benzaldehyde (By similarity).
Synonyms: 10-FTHFDH; FDH; FTHFD; 10-fTHF
Tractability: Small molecule: a structure with a bound ligand is known; it has a binding pocket of medium quality; it belongs to a druggable protein family. PROTAC: its protein half-life has been measured.
Gene: Protein-coding gene on chromosome 3 (126,103,561 to 126,197,994, reverse strand). Ensembl gene ENSG00000144908.
Subcellular location: Cytoplasm, cytosol
Subcellular location (Human Protein Atlas): Cytosol
Pathways (Reactome):
Metabolism: Metabolism of folate and pterines
Gene Ontology:
Molecular function: formyltetrahydrofolate dehydrogenase activity; protein binding; aldehyde dehydrogenase (NAD+) activity; catalytic activity; oxidoreductase activity
Biological process: 10-formyltetrahydrofolate catabolic process; NADPH regeneration; aldehyde metabolic process; one-carbon metabolic process; tetrahydrofolate interconversion
Cellular component: cytosol; extracellular exosome; mitochondrion; cytoplasm
Genetic constraint (gnomAD): Loss-of-function variants: 68 observed, 101.27 expected, observed/expected ratio (o/e) 0.67, 90% interval 0.55 to 0.82. The upper end of that interval is the gene's LOEUF score, 0.82, which puts it in group 3 of 6, group 1 being the genes least tolerant of losing a copy. Missense variants: 1,087 observed, 1,186.8 expected, observed/expected ratio (o/e) 0.92, 90% interval 0.87 to 0.96. Synonymous variants: 486 observed, 485.63 expected, observed/expected ratio (o/e) 1, 90% interval 0.93 to 1.08.
Homologues: Orthologues: chimpanzee ALDH1L1 (99% identical), macaque ALDH1L1 (96% identical), guinea pig ALDH1L1 (92% identical), mouse Aldh1l1 (92% identical), rat Aldh1l1 (92% identical), pig ALDH1L1 (87% identical), rabbit ALDH1L1 (86% identical), tropical clawed frog aldh1l1 (77% identical), zebrafish aldh1l1 (76% identical), Drosophila melanogaster CG8665 (60% identical), Caenorhabditis elegans alh-3 (60% identical), Caenorhabditis elegans alh-1 (28% identical), and 2 more. Paralogues in human: ALDH1L2 (74% identical), ALDH1A2 (29% identical), ALDH1B1 (28% identical), ALDH1A1 (27% identical), ALDH2 (27% identical), ALDH1A3 (27% identical), ALDH9A1 (22% identical), ALDH5A1 (20% identical), ALDH8A1 (20% identical), ALDH7A1 (16% identical), ALDH6A1 (16% identical), ALDH4A1 (15% identical), and 5 more.
Diseases named in the same sentence as ALDH1L1 in open-access papers:
ALDH1L1 is named in the same sentence as 70 diseases in open-access papers, as found by Europe PMC text mining. Sharing a sentence is not in itself a finding about the gene and the disease. The quoted sentences say what the papers report.
hepatocellular carcinoma (14 papers, 2008 to 2025). A malignant tumor that arises from hepatocytes. "In contrast, reduced ALDH1L1 expression in hepatocellular carcinoma is associated with poor prognosis." (PMID 40868269, 2025). "Thus, ALDH1L1 rs1127717 was associated with the increased risk of hepatocellular carcinoma in Chinese population (1500 cancer patients and 1500 controls were enrolled in this study)." (PMID 31737034, 2019). "In hepatocellular carcinoma, decreased ALDH1L1 is associated with a poor prognosis." (PMID 27015121, 2016). "In fact, analyses of recently generated Aldh1l1-deficient mice have shown that Aldh1l1 deficiency significantly affects intracellular metabolism, including one-carbon metabolism, and that this deficiency greatly accelerates tumor incidence in a diethylnitrosamine-induced liver carcinoma mouse model." (PMID 37596270, 2023). "Studies examining gene expression profiles have revealed ALDH1L1 as one of the most under-expressed genes in hepatocellular carcinomas (HCCs) as compared to normal livers." (PMID 39728477, 2024). "ALDH1L1 mRNA and protein expression is significantly reduced in hepatocellular carcinoma, and the low expression of the protein is a potential prognostic marker for hepatocellular carcinoma." (PMID 39478854, 2024). "Here, we investigated the effect of the Aldh1l1 mouse knockout (Aldh1l1−/−) on hepatocellular carcinoma using a chemical carcinogenesis model." (PMID 34203215, 2021). "Remarkably, a microarray-based global gene expression profiling of approximately 42,000 genes has found that ALDH1L1 was one of the most down-regulated proteins in primary hepatocellular carcinomas and in liver metastases." (PMID 31737034, 2019). "ALDH1L1 (aldehyde dehydrogenase 1 family, member L1) is one of the genes which expression is strongly downregulated in many human cancers including hepatocellular carcinoma, pilocytic astrocytoma, liver cancer, renal cell carcinoma, lung adenocarcinoma." (PMID 29868117, 2018). "Other works demonstrated the importance of CpG methylation in suppression of ALDH1L1 in several cancer types and cell lines including lung adenocarcinoma, hepatocellular carcinoma, and esophageal squamous cell carcinoma." (PMID 29868117, 2018). "Downregulation of ALDH1L1 gene at the mRNA and protein levels was observed in hepatocellular carcinoma, pilocytic astrocytoma, liver cancer, and cancer cell lines (A549, HepG2, 293A, Du-145, PC-3)." (PMID 24977159, 2014). "Therefore, suppressed ALDH1L1 expression is correlated with poor prognosis in hepatocellular carcinoma, sporadic pilocytic astrocytoma, and neuroblastoma." (PMID 36336972, 2023). "We focused on aldehyde dehydrogenase 1 family member L1 (ALDH1L1), which metabolizes 10-fTHF to tetrahydrofolate and whose expression is often attenuated in hepatocellular carcinoma (HCC)." (PMID 37596270, 2023). "This hypothesis has found support in our recent study of diethylnitrosamine-induced hepatocellular carcinoma in mice, which indicates that Aldh1l1 knockout promoted liver tumor growth without affecting tumor initiation or multiplicity." (PMID 36500483, 2022).
breast cancer (6 papers, 2018 to 2026). A primary or metastatic malignant neoplasm involving the breast. "Here, we used deep bisulfite sequencing and qPCR analysis to investigate the pattern of CpG methylation of ALDH1L1 promoter region and its association with the gene expression level in 16 paired breast cancer (BC) samples of different clinical stages." (PMID 29868117, 2018). "Similarly, the stratified analysis by hormone receptors indicated that carriers of the C allele of ALDH1L1 rs2002287 present an increased risk of developing breast cancer PR+ (OR = 1.54; 95%IC = 1.04–2.26; p = 0.03)." (PMID 39125744, 2024). "Our study has revealed that NAC dramatically alters epigenetic heterogeneity in breast cancer and induces convergent hypomethylation of stem cell quiescence-associated genes, ALDH1L1, HOPX, WNT5A and SOX9, which can potentially be developed as therapeutic targets or biomarkers for chemoresistance." (PMID 30774927, 2019). "The top target differentiating the Aldh1l2 KO group from the WT/Aldh1l1 KO group is interferon gamma, which would be in agreement with recent findings that interferon signaling is responsive to folate status in murine mammary cancer cells." (PMID 33168096, 2020). "Do ALDH1L1 promoter methylation level or gene expression level correlate with clinical stage of breast cancer?" (PMID 29868117, 2018). "In this work, we demonstrate that ALDH1L1 gene is strongly downregulated in breast cancer (BC) and interrogate the role of methylation status of each individual CpG site within the promoter region in suppression of the gene." (PMID 29868117, 2018). "However, ALDH1L1 showed totally different presentation in distinct types of cancers; mRNA high expressions of ALDH1L1 were reported to be correlated to higher overall survival rate for breast cancer patients but were revealed as a poor prognostic factor in gastric and prostatic cancers." (PMID 32118031, 2020).
lung carcinoma (6 papers, 2016 to 2021). "In the spontaneous lung cancer model by Kras mutation, the ALDH1L1 protein level was increased following to the oncogenesis of adenocarcinoma." (PMID 34066916, 2021). "In the initial experiment, the authors demonstrated the expression of ALDH1L1 protein in A549 lung cancer cells, a highly surprising finding." (PMID 33918472, 2021). "We have provided evidence which demonstrates that an increase in NADH, after over expression of ALDH1L1 by transfection, was shown in lung cancer cell lines." (PMID 34066916, 2021). "Instead of gossypol treatment, the combination of the loss of ALDH1L1 deletion and phenformin treatment decreased tumor growth in an in vivo KRAS-driven lung cancer model, and the synergy correlated with a decrease in ATP production." (PMID 32883024, 2020). "KRAS upregulates the expression of ALDH1L1 in NSCLC cells, which exhibited an increase of ALDH1L1 in Kras-driven lung cancer model." (PMID 32481524, 2020). "In the introduction to their study, the authors cited two papers to suggest that ALDH1L1 is upregulated in lung cancer, but neither of the references show an upregulation of ALDH1L1 in non-small cell lung cancer." (PMID 33918472, 2021). "In summary, targeting ALDH1L1 alone did not have an anti-cancer effect in the KrasLA2 lung cancer model, whereas simultaneous inhibition of ALDH1L1 and oxidative phosphorylation significantly decreased tumor formation." (PMID 32481524, 2020). "Although targeting ALDH1L1 alone did not have an anti-cancer effect in the KrasLA2 lung cancer model, simultaneous inhibition with gossypol and phenformin significantly decreased tumor formation." (PMID 32481524, 2020).
folate deficiency (5 papers, 2019 to 2025). A nutritional condition produced by a deficiency of FOLIC ACID in the diet. "Our previous study revealed that Aldh1l1 knockout (KO) mice have an altered liver metabotype with metabolic symptoms of folate deficiency when fed a standard chow diet containing 2 ppm folic acid." (PMID 35629957, 2022). "Unexpectedly, Aldh1l1 knockout (KO) mice displayed functional folate deficiency despite the fact that they were fed a folate-proficient diet, and the total levels of folate coenzymes were not changed in these mice." (PMID 35629957, 2022). "Moreover, folic acid-deficiency in the maternal diet did not exert significant impacts on folate cycle genes except for Aldh1l1, which was decreased with folic acid deficiency." (PMID 40001612, 2025). "In addition, Aldh1l1 KO mice demonstrated that the loss of the enzyme induces a functional folate deficiency because the THF pool cannot be replenished from the 10-formyl-THF conversion." (PMID 34203215, 2021). "Thus, the Aldh1l1 loss is associated with functional folate deficiency in mouse liver even though the intake of dietary folate was not limited." (PMID 31624291, 2019). "Overall, though the Aldh1l1 KO produces metabolic effects that are indicative of functional folate deficiency, the dietary folate restriction itself does not fully recapitulate the metabolic effect of the KO." (PMID 35629957, 2022). "Though Aldh1l1−/− mice were viable and did not have an apparent phenotype, metabolomic analysis indicated that they had metabolic signs of folate deficiency." (PMID 31624291, 2019). "We recently reported that Aldh1l1 knockout in mice does not lead to any evident phenotype but produces strong metabolic alterations in the liver, evoking metabolic symptoms of functional folate deficiency." (PMID 34203215, 2021).
liver cancer (5 papers, 2014 to 2023). An epithelial or non-epithelial malignant neoplasm that arises from the liver. "In line with our observations in HuH-7 cells, liver cancer cell lines with lower expression of ALDH1L1 were ZMP-sensitive." (PMID 37596270, 2023). "We categorized the liver cancer cell lines into two groups of high and low ALDH1L1 mRNA expression in the public 22Q4 expression data set [high log2 (TPM + 1) > 1.5; low log2 (TPM + 1) < 1.0]." (PMID 37596270, 2023). "It is worth mentioning that cordycepin, which is an AMP analog, was the most sensitive compound within the PRISM repurposing primary screen data set in the lower ALDH1L1-expressing liver cancer cell lines." (PMID 37596270, 2023). "In contrast, downregulation of ALDH1B1 and ALDH1L1 was found in liver cancer compared with normal tissues." (PMID 28792511, 2017). "To examine whether our findings are dependent on ALDH1L1 expression levels or the intrinsic features of HuH-7 cells, we utilized the cancer dependency map (DepMap) tool and analyzed the drug sensitivity of liver cancer cell lines." (PMID 37596270, 2023). "Because it was difficult to compare expression levels with normal tissues based on these database results alone, we compared ALDH1L1 expression levels in 20 cell lines, including 2 liver cancer cell lines, using normal tissue-derived pooled cDNA as a reference." (PMID 37596270, 2023). "The results showed that ALDH1A1, ALDH1L1, ALDH1L2, ALDH3A1, ALDH3A2, ALDH5A1, and ALDH8A1 gene expressions were significantly different between liver cancer and normal tissues." (PMID 34928471, 2022).
non-small cell lung carcinoma (4 papers, 2016 to 2021). A group of at least three distinct histological types of lung cancer, including non-small cell squamous cell carcinoma, adenocarcinoma, and large cell carcinoma. "We demonstrated that the ALDH1L1 gene expression level of cancer samples is higher than that of normal samples in non-small cell lung cancer (a." (PMID 34066916, 2021). "Bioinformatics analysis of metabolic enzymes in non-small cell lung cancer (NSCLC) revealed upregulation of aldehyde dehydrogenase (ALDH) isoforms including ALDH1L1." (PMID 32481524, 2020). "Among ALDH isoforms, ALDH1L1 in the folate pathway showed highly increased expression in non-small-cell lung cancer cells (NSCLC)." (PMID 27384481, 2016).
Stroke (4 papers, 2011 to 2024). Sudden impairment of blood flow to a part of the brain due to occlusion or rupture of an artery to the brain. "Lineage tracing showed that after both SCI and stroke, over 90% of Gfap plus Sox9-positive lesion border astrocytes also expressed Aldh1l1-CreERT-tdT, indicating that these cells derived from local mature astrocytes." (PMID 38907165, 2024). "In contrast, ALDH1L1 was significantly downregulated in the infarct area of both TTC− (p < 0.0001) and TTC+ (p < 0.0001) stroke mice." (PMID 31417355, 2019). "The total number of Aldh1l1+ astrocytes was not significantly different on post-stroke day 3 or 7 compared to sham." (PMID 22132159, 2011). "Cumulatively 11.1±1.2% of Aldh1l1+ astrocytes within 400 μm in the cortical penumbra incorporate BrdU in the first week following stroke, while the overall number of astrocytes does not change." (PMID 22132159, 2011).
depression (3 papers, 2018 to 2024). "In addition, a novel SNP was associated with depression in female individuals: rs114542799 in the intron region of the ALDH1L1 gene on chromosome 3." (PMID 39028994, 2024).
ischemic stroke (3 papers, 2014 to 2019). A stroke disorder caused by obstruction of blood flow to the brain, due to thrombotic (local blood clot formation) or embolic (due to a blood clot or other material traveling from another site) event. "ALDH1L1, another gene of the ‘one-carbon metabolism’ pathway that we found to be up-regulated by Hcy-thiolactone, is associated with ischemic stroke." (PMID 25802182, 2015). "Of these, one variant in the ALDH1L1 locus, rs2364368, was associated with incident ischemic stroke." (PMID 24651765, 2014). "Finally, we identified a novel association between ischemic stroke and ALDH1L1, which emphasizes the clinical importance of this work." (PMID 24651765, 2014).
lung adenocarcinoma (3 papers, 2018 to 2021). A carcinoma that arises from the lung and is characterized by the presence of malignant glandular epithelial cells. "mRNA expression of ALDH1L1 is high in lung adenocarcinoma, but low in other cancers by analysis of TCGA data (unpublished)." (PMID 34066916, 2021). "mRNA expression of ALDH1L1 is high in lung adenocarcinoma, but low in other cancers by analysis of TCGA data." (PMID 34066916, 2021). "Lung adenocarcinoma cells express high levels of ALDH1L1, an enzyme of the one-carbon pathway that catalyzes the conversion of 10-formyltetrahydrofolate into tetrahydrofolate and NAD(P)H." (PMID 32481524, 2020).
prostate carcinoma (3 papers, 2020 to 2023). A carcinoma that arises from epithelial cells of the prostate gland. "Taken together, ALDH1L1 is involved in the controlled mediation of apoptosis in prostate cancer cells." (PMID 34572930, 2021).
amyloid (2 papers, 2022). "To understand how Bmal1-depleted astrocytes behave in the context of Aβ pathology, we examined astrocyte activation in the cortex of BMAL1 aKO mice crossed to the APP/PS1-21 model of Aβ-amyloidosis (Aldh1l1-CreERT2;Bmal1fl/fl;APP/PS1-21)." (PMID 35110643, 2022).
COVID-19 (2 papers, 2023 to 2024). A disease caused by infection with severe acute respiratory syndrome coronavirus 2. "AD patients with COVID-19 also presented with extensive hippocampal astrocyte dysregulation as compared to their Non-COVID counterparts exhibited by our quantifications of GFAP and ALDH1L1." (PMID 39154174, 2024). "We quantified the proportion of ALDH1L1 positive astrocytes that were also positive for YKL-40 and found that there were significantly more YKL-40 positive astrocytes in the hilum of ARDS and COVID-19 brains compared to non-ARDS controls." (PMID 37483351, 2023).
dementia (2 papers, 2021 to 2022). Loss of intellectual abilities interfering with an individual's social and occupational functions. "Aldh1l1 and GFAP were increased in AD, but in patients with dementia with Lewy bodies (DLB), only an Aldh1l1 increase was detected, highlighting different pathological mechanisms between the 2 most commons types of dementia (rather than a common mechanism) with a different astrocytic contribution." (PMID 35250459, 2022).
esophageal squamous cell carcinoma (2 papers, 2018 to 2021). Esophageal squamous cell carcinoma (ESCC) is a type of esophageal carcinoma (EC) that can affect any part of the esophagus, but is usually located in the upper or middle third. "RNA sequencing data from The Cancer Genome Atlas (TCGA) database have revealed downregulated ALDH1A2 and ALDH1L1 expression in esophageal squamous cell carcinoma and HNC squamous cell carcinoma." (PMID 34680942, 2021).
experimental autoimmune encephalomyelitis (2 papers, 2023 to 2025). An autoimmune demyelinating disease of the central nervous system that is produced experimentally in animals by the injection of homogenized brain or spinal cord in Freund's adjuvant. "To further elucidate the role of astrocytic IFNγ signaling on the PD-1/PD-L1 axis in vivo, we induced the experimental autoimmune encephalomyelitis (EAE) model of MS in Aldh1l1-CreERT2, Ifngr1fl/fl mice." (PMID 37828609, 2023). "We tested whether flox‐mediated recombination from Aldh1l1‐Cre/ERT2 occurs in immune cells in addition to astrocytes and whether these cells traffic from the spleen into the spinal cord during experimental autoimmune encephalomyelitis (EAE), a model of CNS autoimmune disease." (PMID 39910805, 2025).
lymph node metastasis (2 papers, 2023 to 2026). "Univariate analysis showed that clinical lymph node metastasis, T stage, Ki‐67, and ALDH1L1 were correlated with OS in patients with OSCC." (PMID 36336972, 2023).